RPS6KB1 (ribosomal protein S6 kinase B1)
Diseases named in the same sentence as RPS6KB1 in open-access papers (continued):
Sharing a sentence is not in itself a finding about the gene and the disease.
lung cancer (68 papers, 2013 to 2026). A malignant neoplasm involving the lung. "RPS6KB1 phosphorylation is related to worse prognosis in patients with nonsmall cell lung cancer." (PMID 37866481, 2023). "Recent studies have reported that the gain of function is the central role of RPS6KB1 in resistance to tyrosine kinase (TKI) in lung cancer, and its specific inhibitor PF-4708671 shows synergistic effect to enhance TKIs efficacy to suppress tumor growth in vivo." (PMID 34727092, 2021). "Increased abundance of ARRB1, as well as FBXO11, LYZ, RPS6KB1, and SYNGR2 have comparable oncogenic effects in hepatocellular carcinoma, and MGST1 and RPS6KB1 have noted oncogenic roles in various lung cancers." (PMID 40186098, 2025). "Our results show that 2HF induced apoptosis in both histological types of lung cancer and inhibited proliferation and growth through suppression of CDK4, CCNB1, PIK3CA, AKT and RPS6KB1 (P70S6K) signaling." (PMID 30546837, 2018).
cardiac hypertrophy (53 papers, 2009 to 2026). "We further demonstrated the role of Rps6kb1 phosphorylation in pathological cardiac hypertrophy and heart failure." (PMID 41505219, 2026). "In conclusion, our findings reveal that the MEK/ERK axis primes Rps6kb1 activation through phosphorylation of 2 separate domains of Rps6kb1, which may play an essential role in cardiac hypertrophy and heart failure under hemodynamic stress." (PMID 41505219, 2026). "In mice, cardiomyocyte-specific deletion of Rps6kb1 significantly inhibited both constitutively active ERK- and pressure overload-induced cardiac hypertrophy." (PMID 41505219, 2026). "In contrast, cardiomyocyte-specific overexpression of wild-type Rps6kb1, rather than the phosphorylation-defective mutant, elevated cardiac hypertrophy and augmented pressure overload-induced heart failure." (PMID 41505219, 2026).
gastric cancer (49 papers, 2009 to 2025). A primary or metastatic malignant neoplasm involving the stomach. "Previous studies on astrocytomas, gastric cancer and esophageal squamous cell carcinoma also identified the phosphorylated RPS6KB1, but not total RPS6KB1, as a novel unfavorable prognosis indicator." (PMID 28792981, 2017).
melanoma (49 papers, 2005 to 2025). A malignant, usually aggressive tumor composed of atypical, neoplastic melanocytes. "For melanoma, the patients with low HSP90AB1 and MME expression in metastatic tumor samples and the patients with low RPS6KB1 expression in primary tumor samples were correlated with significantly longer survival than the corresponding high expression cohorts." (PMID 38578805, 2024).
hepatocellular carcinoma (47 papers, 2012 to 2025). A malignant tumor that arises from hepatocytes. "The Transwell migration and invasion assays showed that there was little difference between the PPM1H-overexpressing and control groups after PF-4708671 addition, indicating that PPM1H regulates the growth of hepatoma cells through inhibition of RPS6KB1." (PMID 37456776, 2023). "Overexpression of RPS6KB1 plays an important role in hepatocellular carcinoma and correlates with adverse prognosis." (PMID 28330331, 2016). "In this study, PPM1H inhibited phosphorylation of SMAD1 and RPS6KB1 in hepatoma cells." (PMID 37456776, 2023). "In our study, p-RPS6KB1 could be directly dephosphorylated by PPM1H in hepatoma cells." (PMID 37456776, 2023). "We discovered RPS6KB1 as a new PPM1H dephosphorylation substrate, which might play an important role in regulation of hepatoma cell development." (PMID 37456776, 2023).
glioblastoma (43 papers, 2010 to 2025). The most malignant astrocytic tumor (WHO grade IV). "EVA1A inhibits glioblastoma cells proliferation by upregulating autophagy via suppressing the mTOR/RPS6KB1 pathway." (PMID 35743108, 2022). "The results showed that miR-30e expression level negatively correlated to RPS6KB1 level in invasive breast carcinoma (BRCA), glioblastoma multiforme (GBM), and lung adenocarcinoma (LUAD)." (PMID 34727092, 2021).
pancreatic cancer (35 papers, 2002 to 2025). "Similarly, the boswellic acid analog BA145 suppressed the T389 phosphorylation of RPS6KB1 in pancreatic cancer, leading to cell cycles distribution and inducing cell apoptosis, which is consistent with our findings." (PMID 28792981, 2017).
bladder cancer (31 papers, 2011 to 2025). "Our findings suggest that TalaA-attenuated RPS6KB1 phosphorylation would contribute to inhibit bladder cancer." (PMID 37866481, 2023).
breast tumors (30 papers, 2004 to 2025). "RPS6KB1 gene amplification and overexpression is reported in about 8–10% of breast tumors and other cancers and correlates with poor prognosis." (PMID 36189922, 2022). "An intra-chromosomal gene fusion involving the estrogen receptor alpha gene ESR1, and another involving the RPS6KB1 (Ribosomal protein S6 kinase beta-1) were recurrently expressed in a number of breast tumor cell lines and a clinical tumor sample." (PMID 22496636, 2012). "Recurrent amplification of 17q23.2 in some breast tumors has recently been reduced to a 249 kb minimal region including potential tumor driver genes, RPS6KB1 and mir-21." (PMID 20423517, 2010).
non-small cell lung carcinoma (26 papers, 2010 to 2025). A group of at least three distinct histological types of lung cancer, including non-small cell squamous cell carcinoma, adenocarcinoma, and large cell carcinoma. "This might explain why RPS6KB1 fusion has not been reported in any non-small cell lung cancer tumor in any peer-reviewed literature." (PMID 40091373, 2025).
neuroblastoma (20 papers, 2013 to 2025). Neuroblastoma (NB) is the most common solid, extracranial childhood tumor. "Similarly, Hcy treatment caused significant increases in the level of MTOR phosphorylation and its downstream substrates RPS6KB1/p70S6K and EIF4EBP1 in human neuroblastoma SH-SY5Y cells." (PMID 27929536, 2016).
osteosarcoma (20 papers, 2015 to 2025). A usually aggressive malignant bone-forming mesenchymal neoplasm, predominantly affecting adolescents and young adults. "Taken together, these data suggest that the proliferative effect of PAFAH1B3 in osteosarcoma is related to the regulation of the expression of EIF4EBP1, MYC, PTGS2 and RPS6KB1." (PMID 34136395, 2021). "Furthermore, the proliferative effect of PAFAH1B3 in osteosarcoma was related to the regulation of the expression of EIF4EBP1, MYC, PTGS2 and RPS6KB1." (PMID 34136395, 2021).
esophageal squamous cell carcinoma (18 papers, 2014 to 2024). Esophageal squamous cell carcinoma (ESCC) is a type of esophageal carcinoma (EC) that can affect any part of the esophagus, but is usually located in the upper or middle third. "We found that higher RPS6KB1 expression levels were strongly associated with lower overall survival rate of esophageal adenocarcinoma and esophageal squamous cell carcinoma patients by Kaplan Meier plotter analysis." (PMID 34727092, 2021).
sarcopenia (17 papers, 2014 to 2025). Progressive decline in muscle mass due to aging which results in decreased functional capacity of muscles. "This is why mTOR and Rps6kb1 can be associated with severe sarcopenia positively and negatively, respectively." (PMID 39585121, 2024). "However, to our knowledge, there is no publication where both of these proteins (mTOR and Rps6kb1) are studied in relation to sarcopenia." (PMID 39585121, 2024).
esophageal cancer (14 papers, 2017 to 2025). A primary or metastatic malignant neoplasm involving the esophagus. "High expression of RPS6KB1 in tumor tissues indicates a poor prognosis with poor survival in esophageal cancer patients." (PMID 37056387, 2023). "Taken together, these results suggest that miR-30e suppresses tumor growth and inhibits RPS6KB1 expression in vivo, and RPS6KB1 acts as an oncogene in esophageal cancer." (PMID 34727092, 2021). "The results showed that RPS6KB1 levels were upregulated in most types of cancer, including colon adenocarcinoma, esophageal carcinoma, head and neck squamous cell carcinoma, lung adenocarcinoma, lung squamous cell carcinoma, stomach adenocarcinoma." (PMID 34727092, 2021). "RPS6KB1::VMP1 (NSCLC P13041) translocation is a recurrent event in esophageal cancer." (PMID 40661875, 2025). "Furthermore, RPS6KB1-mediated Gli1 at Ser84 (downstream hedgehog pathway effector) phosphorylation promoted esophageal cancer development." (PMID 34727092, 2021). "To further determine whether the expression of miR-30e novel target RPS6KB1 is relevant with human esophageal cancer, we studied expression levels of RPS6KB1 in the cancer tissues and the cancer outcome." (PMID 34727092, 2021). "In the context of human samples of esophageal cancer analyzed through RNA sequencing, polymerase chain reaction (PCR), and Sanger sequencing techniques, a notable finding involves the fusion of VMP1 with Ribosomal Protein S6 Kinase B1 (RPS6KB1)." (PMID 38612567, 2024).
Hepatic steatosis (13 papers, 2016 to 2026). Steatosis is a term used to denote lipid accumulation within hepatocytes. "RPS6KB1, a kinase linked to various cellular processes and protein synthesis, has demonstrated associations with conditions such as fatty liver disease, intestinal disorders, and oxidative stress pathways." (PMID 38201907, 2023).
esophageal adenocarcinoma (12 papers, 2014 to 2024). A malignant tumor with glandular differentiation arising predominantly from Barrett mucosa in the lower third of the esophagus. "Firstly, the RPS6KB1/VMP1 fusion is suggested to result in a dysfunctional protein incapable of inducing autophagy in esophageal adenocarcinoma." (PMID 38612567, 2024). "In esophageal adenocarcinoma, the RPS6KB1/VMP1 fusion has been found in around 10% of cases." (PMID 38612567, 2024).
lung adenocarcinoma (11 papers, 2013 to 2025). A carcinoma that arises from the lung and is characterized by the presence of malignant glandular epithelial cells. "Indeed, an analysis of TCGA data using cBioPortal reveals that RPS6KB1 and RPS6KB2, the two isoforms of P70S6K, are amplified or over-expressed in 20% and 11% of lung adenocarcinoma cases, respectively." (PMID 32513387, 2020).
acute myeloid leukemia (10 papers, 2010 to 2025). Acute myeloid leukemia (AML) is a group of neoplasms arising from precursor cells committed to the myeloid cell-line differentiation. "Finally, the activation interaction between mTOR and RPS6KB1 in the ‘acute myeloid leukemia’ pathway was predicted to be of phosphorylation type by our method." (PMID 24625764, 2014).
brain tumor (10 papers, 2005 to 2025). "In brain tumors, correlated RPS6KB1 and hypoxia-responsive genes are upregulated, and RPS6KB1 is associated with a poor prognosis for these patients." (PMID 37456776, 2023). "S6K1 gene (RPS6KB1) is significantly overexpressed in different brain tumours compared with normal brain tissue in 4 independent studies." (PMID 22570651, 2012).
psoriasis (10 papers, 2015 to 2024). An autoimmune condition characterized by red, well-delineated plaques with silvery scales that are usually on the extensor surfaces and scalp. "In psoriasis lesional skin RPS6KB1 mRNA expression was 3.2-fold lower (p < 0.001) and in psoriasis non-lesional skin it was 3.0-fold lower (p < 0.05) compared with healthy control skin." (PMID 34884858, 2021). "Decreased RPS6KB1 mRNA expression in lesional as well as in non-lesional skin of psoriasis patients was established." (PMID 34884858, 2021).
endometrial cancer (7 papers, 2012 to 2024). Primary or metastatic malignant neoplasm involving the endometrium (mucous membrane that lines the endometrial cavity). "A significant correlation was also evident between LDHA and RPS6KB1 expression in endometrial cancer tissue (p = 0.01)." (PMID 39394200, 2024).
lymphoma (7 papers, 2005 to 2025). A malignant (clonal) proliferation of B- lymphocytes or T- lymphocytes which involves the lymph nodes, bone marrow and/or extranodal sites. "In addition, RPS6KB1 has been viewed as a potential biomarker for aggressive malignant lymphoma, especially in patients with HIV, and has also been associated with the development of multiple sclerosis in Iranian populations." (PMID 40723577, 2025).
squamous cell carcinoma (7 papers, 2015 to 2020). A carcinoma arising from squamous epithelial cells. "LY2584702 was used to inhibit the phosphorylation of RPS6KB1 in pulmonary adenocarcinoma cell line A549 and squamous cell carcinoma cell line SK-MES-1." (PMID 28792981, 2017).
thyroid cancer (6 papers, 2014 to 2024). "miR-153 is involved in inhibiting proliferation and development of thyroid carcinoma by targeting RPS6KB1 in the mTOR-dependent pathway." (PMID 36158686, 2022). "Furthermore, ribosomal protein S6 kinase B1 (RPS6KB1) is a serine/threonine kinase in downstream of mTOR pathway, implicated in cell viability and inhibition of apoptosis through phosphorylating BAD protein in thyroid carcinoma." (PMID 36158686, 2022).
diffuse large B-cell lymphoma (5 papers, 2017 to 2025). "This contrasts with RPS6KB1, which shows elevated expression in cholangiocarcinoma, diffuse large B-cell lymphoma (DLBCL), and thymoma (THYM)." (PMID 39796034, 2024).
metastatic disease (5 papers, 2010 to 2025). "Thus, it is reasonable that the low expression of HSP90AB1 and MME in metastatic but not primary tumor samples and the low RPS6KB1 expression in primary but not metastatic tumor samples are correlated with prolonged survival." (PMID 38578805, 2024).
Parkinson disease (5 papers, 2010 to 2023). A progressive degenerative disorder of the central nervous system characterized by loss of dopamine producing neurons in the substantia nigra and the presence of Lewy bodies in the substantia nigra and locus coeruleus. "Corynoxine can regulate several kinases, including RPS6KB1, MAP2K2, and PLK1, contributing to the clearance of AD-associated β-amyloid precursor protein (APP) and Parkinson disease-associated α-synuclein." (PMID 33807157, 2021).
small cell lung carcinoma (5 papers, 2007 to 2023). Small cell lung cancer (SCLC) is a highly aggressive malignant neoplasm, accounting for 10-15% of lung cancer cases, characterized byrapid growth, and early metastasis. "Similarly, the levels of phosphorylated RPS6KB1/p70S6K were elevated in the small cell lung cancer cells that acquired resistance to cisplatin, and activation of RPS6KB1/p70S6K contributes to cisplatin resistance." (PMID 34645978, 2021).
hemangioma (4 papers, 2007 to 2021). A benign vascular lesion characterized by the formation of capillary-sized or cavernous vascular channels. "In particular, tsc1+/- or tsc2+/- mutant mice which are characterized by high level of mTOR-mediated phosphorylation of Eif4ebp1 and Rps6kb1, have hemangiomas with poorly developed vasculature that are prone to rupture." (PMID 17892597, 2007).
pulmonary fibrosis (4 papers, 2021 to 2025). Chronic progressive interstitial lung disorder characterized by the replacement of the lung tissue by connective tissue, leading to progressive dyspnea, respiratory failure, or right heart failure. "Compared with the control group, the BLM-induced pulmonary fibrosis group exhibited significantly higher expression of Fmod and Tgfbr2 mRNA; in contrast, the mRNA expression levels of Bambi, Skp1, Zfyve9, Zfyve16, Ppp2ca, Ppp2r1a, Ppp2r1b, Rps6kb1, and Rps6kb2 were markedly lower." (PMID 38259493, 2023).
systemic lupus erythematosus (4 papers, 2015 to 2023). An autoimmune multi-organ disease typically associated with vasculopathy and autoantibody production. "Signaling by the PI3K/Akt/mTOR pathway profoundly affects mRNA translation through phosphorylation of downstream targets such as 4E-BP and RPS6KB1; we further explored the level of phosphorylation of 4E-BP1 and RPS6KB1 in lymphocytes of mouse models of lupus with IGFBP2 blockade treatment." (PMID 36008635, 2022).
fragile X syndrome (3 papers, 2013 to 2023). A genetic syndrome caused by mutations in the FMR1 gene which is responsible for the expression of the fragile X mental retardation 1 protein. "RPS6KB1 may be particularly important in the context of neurodevelopment because genetic ablation of this gene rescues multiple physiological and behavioural phenotypes in a mouse model of fragile X syndrome, caused by aberrant synaptic translation." (PMID 24058414, 2013).
medulloblastoma (3 papers, 2012 to 2020). A malignant, invasive embryonal neoplasm arising from the cerebellum. "Furthermore, they found significantly elevated transcript levels of RPS6KB1 as compared to normal cerebellum in 5 out of 6 desmoplastic medulloblastomas and in 4 out of 5 classic medulloblastomas analysed." (PMID 25885658, 2015).
pancreatic ductal adenocarcinoma (3 papers, 2017 to 2023). An infiltrating adenocarcinoma that arises from the epithelial cells of the pancreas. "So the negative effect of RPS6KB1 in pancreatic ductal adenocarcinoma and kidney cancer might not weaken the crucial role of RPS6KB1 in NSCLC." (PMID 28792981, 2017). "In pancreatic ductal adenocarcinoma, neither RPS6KB1 nor p-RPS6KB1 was prognostic." (PMID 28792981, 2017).
rectal cancer (3 papers, 2015 to 2017). A primary or metastatic malignant neoplasm that affects the rectum. "Additionally, RPS6KB1 rs180515 exhibited synergistic epistasis (crude ORinteraction = 1.19) with PRKAG2 rs1104897, but RPS6KB1 rs180519 showed suppressive epistasis (crude ORinteraction = 0.80) with PIK3CA rs7640662 in rectal cancer susceptibility." (PMID 27588484, 2016).
cardiac arrhythmia (2 papers, 2021 to 2025). Any disturbances of the normal rhythmic beating of the heart or MYOCARDIAL CONTRACTION. "Upon searching the Open Targets platform, we identified 10 known small molecule drugs in clinical trials (including LY2584702) that are linked to two proteins (RPS6KB1 and MMP12), targeting various cancers, chronic hepatitis C infection and chronic obstructive pulmonary disease." (PMID 40092369, 2025).
cholangiocarcinoma (1 paper, 2024). A carcinoma that arises from the intrahepatic biliary tree (intrahepatic cholangiocarcinoma) or from the junction, or adjacent to the junction, of the right and left hepatic ducts (hilar cholangiocarcinoma). "However, head and neck cancers and cholangiocarcinoma displayed a higher frequency of RPS6KB2 alterations compared to RPS6KB1." (PMID 39796034, 2024).
COVID-19 (1 paper, 2024). A disease caused by infection with severe acute respiratory syndrome coronavirus 2. "Inspired by this network analysis, we queried the STRING database by including p70S6K (gene name RPS6KB1) and mTOR as representative proteins for the PI3K/mTOR pathway, along with a list of closely related COVID-19 proteins based on the DISEASES database." (PMID 39513867, 2024).